GSK3B (glycogen synthase kinase 3 beta)
Diseases named in the same sentence as GSK3B in open-access papers (continued):
Sharing a sentence is not in itself a finding about the gene and the disease.
malignant glioma (5 papers, 2011 to 2025). A grade III or grade IV glioma arising from the central nervous system. "We also showed that the GSK-3β/β-catenin signaling pathway and related antiapoptotic genes play critical roles in regulating cell survival or cell death events in malignant glioma cells, and are the key factors in the development of apoptosis resistance." (PMID 22046442, 2011). "GSK-3β, therefore, was considered as a potential therapeutic target in malignant glioma." (PMID 22046442, 2011).
myeloid leukemia (5 papers, 2012 to 2025). A clonal proliferation of myeloid cells and their precursors in the bone marrow, peripheral blood, and spleen. "In myeloid leukemia cells and macrophages, CaMK4 phosphorylates and inhibits GSK3β, preventing proteasomal degradation of mTOR." (PMID 36002021, 2022). "Although a previous report shows that knockdown or inhibition of Sirt2 with AC93253 in myeloid leukemia cells activates GSK3β through decreased Ser9 phosphorylation and prevents aberrant proliferation, little is known about the role of Sirt2 and GSK3β in ESCs." (PMID 24204656, 2013). "This inhibitory phosphorylation of GSK-3β is an early step in the ATRA-induced differentiation of myeloid leukemia cells, in keeping with the importance of inhibition of activity of GSK-3β to cell differentiation." (PMID 23213553, 2012).
pancreatic adenocarcinoma (5 papers, 2010 to 2024). "Although elevated expression of GSK-3β was observed, abnormal nuclear localization of β-catenin was also monitored in pancreatic adenocarcinoma." (PMID 36829596, 2023). "GPX1 inhibits the EMT by regulating the Akt/GSK3β/Snail signaling axis in pancreatic adenocarcinoma (PDAC)." (PMID 35178395, 2021).
pulmonary hypertension (5 papers, 2011 to 2024). Increased pressure within the pulmonary circulation due to lung or heart disorder. "Our data are in agreement with previous studies showing that the activation of phosphorylated GSK-3β/β-catenin activity is involved in the beneficial effects of ghrelin against hypoxia-induced pulmonary hypertension in the rat and ischemic neural injury." (PMID 25866509, 2015). "Expression of Wnt ligands (Wnt1, Wnt3a, and Wnt5a) and Wnt signaling upstream regulator genes (Frizzled1 and 2 receptors and sFRP-1) and intracellular effectors (Axin1 and GSK3β) were investigated in pulmonary hypertensive rat lungs, 3 and 5 weeks after MCT injury." (PMID 21533110, 2011). "Therefore, we speculate that Ato may be a new therapeutic target in the treatment of pulmonary hypertension by regulating GSK-3β mediated HK-2." (PMID 33886502, 2021).
sarcoma (5 papers, 2012 to 2021). A usually aggressive malignant neoplasm of the soft tissue or bone. "In particular, we found a key role for GSK-3β, which results in up-regulation in tumor versus normal tissue samples and associated to poor prognosis in sarcoma patients." (PMID 34681807, 2021). "In this context, TCN, an AKT inhibitor, which also decreased phosphorylation of AKT and GSK3β at ser9, diminished as well growth in both sarcoma cell lines similar to UA." (PMID 27219337, 2016). "The loss of VAPB/PTPIP51 interaction occurs through increased activation of GSK3β, as already demonstrated both in TDP-43 or fused in sarcoma (FUS) models, although the mechanism is still obscure." (PMID 34769284, 2021). "After short-term treatments (6 or 9 h) with UA a strong AKT inhibition with concomitant GSK3β activation and reduced β-catenin levels could be detected in synovial SW982 sarcoma cells." (PMID 27219337, 2016). "Overall, based on prognostic values in sarcoma patients, overexpression in soft tissue sarcomas as compared with normal tissues and the sensitivity of the epithelioid sarcoma cell line to CHIR99021, we considered GSK-3β a potential drug target worthy of further investigation." (PMID 34681807, 2021). "In sarcoma cells, we found reductions in the protein levels of positive effectors of the Wnt pathway (β-catenin, TCF4, c-MYC and WNT1) and increases in those of negative effectors (GSK3-β and AXIN1) in cells overexpressing EMX proteins." (PMID 34364391, 2021).
skin cancer (5 papers, 2010 to 2017). "CGE controlled skin cancer cell growth by inhibiting the PI3K/AKT/GSK-3β signaling pathway and activating the effector caspases." (PMID 24325618, 2013). "Inactivated GSK-3β promoted mammary tumorigenesis, whereas activated GSK-3β was essential for tumor growth of skin cancer and medullary thyroid cancer." (PMID 20704706, 2010).
steatosis (5 papers, 2011 to 2021). Increased lipid within the cytoplasm of cells. "The mechanism of Akt-dependent steatosis involves a number of down-stream effectors including GSK3β and FoxO1." (PMID 21479224, 2011). "Increased expression levels of phospho-GSK-3β, β-catenin and TCF4 induced by exendin-4 treatment were observed in an in vitro model of steatosis." (PMID 27907035, 2016).
tongue cancer (5 papers, 2015 to 2022). A malignant neoplasm affecting the tongue. "Overexpression of EZH2 and downregulation of H19 completely reversed H19 silencing-mediated inhibition of β-Catenin and GSK-3β activation in tongue cancer cells." (PMID 33052244, 2020). "In order to explore the mechanisms responsible for 14-3-3σ sensitizing TC cells to chemotherapy, we focused on GSK3β/β-catenin signaling, because our previous data suggested activation of GSK3β/β-catenin signal in multidrug resistant tongue cancer (MDR-TC) cells Tca8113/PYM." (PMID 26036631, 2015). "GSK3β also is a positive prognostic marker for tongue cancer patients." (PMID 26036631, 2015). "To further verify the inhibitory effect of activated GSK-3β on tongue cancer, we used the selective GSK-3β inhibitor kenpaullone (KP) to treat IL-18-transfected CRL1623 cells and found that KP reduced GSK-3β phosphorylation and its activation, in turn inhibiting the activity of caspase-3 and -7." (PMID 25591548, 2015).
Ventricular arrhythmia (5 papers, 2013 to 2023). "Our present study shows for the first time that chronic treatment for 4 weeks with NAC leads to preserved Cx43 phosphorylation, total amount and function probably through a cAMP-dependent GSK-3β pathway and attenuates ventricular arrhythmias in infarcted rats." (PMID 24015194, 2013). "In this report, we show that Cx43 activated through the inactivation of glycogen synthase kinase-3β (GSK-3β) by NAC-induced cAMP-PKA and cAMP-Epac signaling attenuated ventricular arrhythmias after MI." (PMID 24015194, 2013).
acute leukemia (4 papers, 2017 to 2024). A clonal (malignant) hematopoietic disorder with an acute onset, affecting the bone marrow and the peripheral blood. "Reduced GSK-3β expression has been previously associated with the development of acute leukemia in mice where removal of GSK-3β expression lead to aggressive AML through altered Wnt/Akt/mTOR signalling." (PMID 28918518, 2017). "The two GSK-3 paralogs, GSK-3α and GSK-3β, have variably been reported to have tumor suppressor and oncogenic properties in different acute leukemia types and subtypes." (PMID 38284896, 2024). "In our study, we found that p-BCR-ABL and classical Wnt/β-catenin signaling were significantly down-regulated (i.e., Dvl-2 and β-catenin were significantly down-regulated and p-GSK3β was significantly up-regulated) when CFTR protein was reduced by CFTRinh-172 and shRNA in Ph+ acute leukemia cells." (PMID 28445932, 2017).
acute lung injury (4 papers, 2017 to 2024). A condition of lung damage that is characterized by bilateral pulmonary infiltrates (pulmonary edema) rich in neutrophils, and in the absence of clinical heart failure. "Correspondingly, an alternative rat model indicated that MIRI-induced acute lung injury (ALI) was associated with GSK3β activation (i.e., decreased p-GSK3β-Ser9 levels), while the beneficial effects of ischemic post-conditioning were associated with restored GSK3β-Ser9 phosphorylation." (PMID 39125833, 2024).
anaplastic thyroid carcinoma (4 papers, 2016 to 2025). "In hypoxic condition, secretion of IL-11, is induced in anaplastic thyroid carcinoma cells and IL-11 activates PI3K/AKT/glycogen synthase kinase 3 β (GSK3β) and results in EMT phenotype." (PMID 28718842, 2017).
Atrophy (4 papers, 2016 to 2023). Any weakening or degeneration, especially through lack of use. "Skeletal muscle atrophy is caused by an imbalance of protein synthesis and degradation, and GSK-3β has been shown to function in glucocorticoid-induced muscle atrophy." (PMID 32937135, 2020). "A great body of evidence is related to the possible contribution of GSK-3β to skeletal atrophy/cachexia atrophy without focusing on the integration with mitochondria." (PMID 26785133, 2016).
autism spectrum disorder (4 papers, 2023 to 2025). A spectrum of developmental disorders that includes autism, and Asperger syndrome. "Interestingly, mice treated with valproic acid as a model of autism spectrum disorder have a decrease in cerebellar GSK3β phosphorylation, which was reversed by PGRN treatment in an Akt-dependent manner." (PMID 37443837, 2023). "The inhibition of GSK-3β via targeting the IL-6-mediated PI3/AKT/mTOR pathway decreases neural apoptosis and affects autism spectrum disorder via GRPR." (PMID 40843259, 2025). "Noteworthily, 21 proteins are related to autism spectrum disorders (e.g. PAK2), intellectual disability (e.g. PAK1), neurodevelopmental disorders (e.g. GSK3β) and epileptic encephalopathies (e.g. MAP1B)." (PMID 37830910, 2023). "IL-6 activates other signaling pathways, such as the PI3K/AKT/the mammalian target of rapamycin (mTOR) glycogen synthase kinase-3 beta (GSK-3β) and gastrin-releasing peptide (GRP) receptor (GRPR) pathways, in hippocampal neurons of mice with autism spectrum disorder." (PMID 40843259, 2025).
cholesteatoma (4 papers, 2020 to 2025). A pathologic process characterized by the proliferation of keratinizing squamous epithelium resulting in the accumulation of keratin and cells in the middle ear and/or mastoid. "For example, one study indicated that the PDK1/PTEN/AKT/GSK3β/CyclinD1 pathway was involved in the proliferation of keratinocytes in cholesteatoma." (PMID 41369408, 2025). "Another study also revealed that PPARδ/PDK1/PTEN/AKT/GSK3β/Cyclin D1 pathway was involved in the proliferation of keratinocytes in cholesteatoma." (PMID 35151320, 2022). "Taken together, our findings indicate that PPAR β/δ activation promotes cell proliferation in cholesteatoma keratinocytes through the regulation of the PDK1/AKT/PTEN/GSK3β/Cyclin D1 pathway." (PMID 33424958, 2020). "Overall, our data suggested that the proliferating effect of PPAR β/δ on the cholesteatoma keratinocytes was mediated by the positive regulation of the PDK1/PTEN/AKT/GSK3β/Cyclin D1 pathway." (PMID 33424958, 2020). "The immunoblot showed that the GW0742 treatment increased the P-AKT (ser473) and its downstream effector Cyclin D1 and inhibited the level of PTEN, with altering phosphorylation activity of GSK3β in the cholesteatoma keratinocytes." (PMID 33424958, 2020). "In summary, we demonstrated that ligand activation of PPAR β/δ regulates cell proliferation in cholesteatoma keratinocytes and that upregulation of PDK1 and modulation of the AKT/PTEN/GSK3β/Cyclin D1 pathway may be involved." (PMID 33424958, 2020).
chronic heart failure (4 papers, 2017 to 2025). "While earlier investigations focused primarily on chronic heart failure and long-term remodeling, growing evidence now supports a critical role for GSK-3β dysregulation in acute myocardial stress and injury." (PMID 40710791, 2025). "The Qiliqiangxin capsule activates the PI3K/AKT/Gsk3β signaling pathway by decreasing ROS and downregulating the expression of apoptosis-related proteins Fas and caspase-3, and inhibits the apoptosis of cardiomyocytes of rats with chronic heart failure." (PMID 38716483, 2024). "Therefore, it needs to be tested if the pro-regenerative effect of PPARδ activation can be enhanced by GSK3β inhibitors in vivo, as we have observed in vitro, and whether this treatment is effective if applied after injury or during chronic heart failure." (PMID 28621328, 2017).
chronic rhinosinusitis (4 papers, 2017 to 2024). Chronic form of sinusitis. "More recently, hsa-miR-335-5p is shown to reduce inflammation via negative regulation of the TPX2-mediated AKT/GSK3β signaling pathway in a chronic rhinosinusitis mouse model." (PMID 33032623, 2020). "For example, in the chronic rhinosinusitis mouse model, upregulation of miR-335 reduced inflammation via negative regulation of the TPX2-mediated AKT/GSK3β signaling pathway." (PMID 39305404, 2024).
colorectal adenoma (4 papers, 2016 to 2023). An adenoma that arises from the colon or rectum. "Few studies explored the effect of folic acid on GSK-3β; some of them indicated that folic acid could regulate GSK-3β Ser9 phosphorylation or GSK-3β expression in model of cardiac teratogenicity or patients with colorectal adenomas." (PMID 28422052, 2017).
dermatitis (4 papers, 2016 to 2023). An inflammatory process affecting the skin. "Other cell signaling pathways including cell cycle and NF-kB pathway (CCND1), autophagy (ATG16L2, ATG10), wnt/β-catenin (APC, GSK3β) and angiogenesis (EDN1) regulating genes were associated with RT related acute mucositis and dermatitis." (PMID 37954025, 2023). "Our study is the first time to show a relationship between GSK3β rs3755557 and radiation-induced dermatitis, but further investigation is needed to delineate the precise mechanism." (PMID 27769064, 2016). "Our findings show that AS-IV induces melanogenesis through AhR-dependent AKT/GSK-3β/β-catenin pathway activation and could be beneficial in the therapy for depigmented skin disorders." (PMID 33381211, 2020).
dilated cardiomyopathy (4 papers, 2017 to 2021). Cardiomyopathy which is characterized by dilation and contractile dysfunction of the left and right ventricles. "Previous studies have shown that the lack of GSK-3β phosphorylation in response to pressure overload is associated with reduced hypertrophy and development of dilated cardiomyopathy, highlighting the important role of GSK-3β phosphorylation in the development of compensatory hypertrophy." (PMID 28115595, 2017). "We found that phosphorylation of GSK3β at S389 was increased in left ventricular samples from patients with dilated cardiomyopathy and ischemic cardiomyopathy, and in hearts of mice subjected to thoracic aortic constriction." (PMID 34948382, 2021). "Cardiac myocyte-specific deletion of GSK3α and GSK3β, together, results in severe dilated cardiomyopathy." (PMID 29504933, 2018).
Dyskinesia (4 papers, 2014 to 2022). A movement disorder which consists of effects including diminished voluntary movements and the presence of involuntary movements. "Other top kinases, such as MAP kinases and GSK3B, have also been implicated in Parkinsonian pathology or levodopa-induced dyskinesia via modulation of postsynaptic dopamine signaling in the striatal MSNs39,40." (PMID 30886221, 2019). "Moreover, previous studies have suggested that dyskinesia induced by chronic L-DOPA treatment in PD can be ameliorated by the inhibition of GSK3β." (PMID 36168204, 2022). "However, in animal models of L-dopa-induced dyskinesia, there is still limited data on GSK-3β expression involve in development of LID." (PMID 26997328, 2016). "Consequently, these data indicated that GSK-3β played a pivotal role in molecular priming for dyskinesia by L-dopa and aberrant D1-dependent molecular plasticity in the striatum." (PMID 26997328, 2016). "Moreover, increase in pAkt(Ser473)/Akt and pGSK3β(Ser9)/GSK3β ratios was observed in the l-DOPA-treated MPTP group, this was prevented with the addition of MPEP and positive correlations were observed between these levels and mean dyskinesia scores." (PMID 25140165, 2014).
endothelial dysfunction (4 papers, 2016 to 2024). In vascular diseases, endothelial dysfunction is a systemic pathological state of the endothelium (the inner lining of blood vessels) and can be broadly defined as an imbalance between vasodilating and vasoconstricting substances produced by (or acting on) the endothelium. "Experimental data and clinical studies in CKD indicate that leptin in high concentrations can produce endothelial dysfunction by modifying the f-actin cytoskeleton through a mechanism involving the protein kinase B/glycogen synthase kinase β (AKT/GSK3β), nitric oxide, and β-catenin pathway." (PMID 39062887, 2024). "Additionally, we describe the phosphorylation and disassembly of β-catenin from the cadherin–catenin complex, correlating with the requirement of GSK-3β for NS1-mediated endothelial dysfunction, and its mislocalization in NS1-treated cells." (PMID 35745469, 2022). "Therefore, amplification of both of these processes by suppressing GSK3β may potentially reduce endothelial dysfunction." (PMID 27534430, 2016).
head and neck cancer (4 papers, 2017 to 2025). A primary or metastatic malignant neoplasm affecting the head and neck. "It indicated that Gsk3β was involved in determining and maintaining stemness of CSCs in head and neck cancer." (PMID 28076327, 2017). "In head and neck cancers, the inhibition of Gsk3β also reduced the expressions of stem cells markers such as Oct4, Sox2, and Nanog, but increased the levels of differentiation markers Calgranulin B and Involucrin in CD44high/ESAhigh cells fraction." (PMID 28076327, 2017). "In head and neck cancer, CD44 was shown to inhibit the phosphorylation of GSK3β, which is required to maintain stem cell self-renewal." (PMID 38329386, 2024).
idiopathic pulmonary fibrosis (4 papers, 2012 to 2025). Idiopathic pulmonary fibrosis (IPF) is a nonneoplastic pulmonary disease that is characterized by the formation of scar tissue within the lungs in the absence of any known cause. "Moreover, in idiopathic pulmonary fibrosis (IPF), inhibiting AKT/GSK3β signaling significantly increases apoptosis rates in pulmonary fibroblasts." (PMID 41509070, 2025). "GSK-3β inhibition via 9-ING-41 has shown anti-fibrotic effects in in vitro and in vivo models of idiopathic pulmonary fibrosis (IPF)." (PMID 34356465, 2021).
Impaired glucose tolerance (4 papers, 2012 to 2021). An abnormal resistance to glucose, i.e., a reduction in the ability to maintain glucose levels in the blood stream within normal limits following oral or intravenous administration of glucose. "Decreased phosphorylation levels of Akt and GSK3β coincide with impaired glucose tolerance in the liver of LKO mice." (PMID 34684470, 2021).
insulinoma (4 papers, 2011 to 2022). "In this study co-incubation of insulinoma cells with an adenovirus expressing a kinase dead Gsk3β (Adv-Gsk3βKM) along with high glucose and palmitate for 24 hours significantly reduced cleaved Caspase3 and cell death." (PMID 21541314, 2011).